TIPE2 (TNF alpha induced protein 8 like 2)
Diseases named in the same sentence as TIPE2 in open-access papers (continued):
Sharing a sentence is not in itself a finding about the gene and the disease.
tumor (37 papers, 2013 to 2026). "Although the TCGA tumor data shows positive relationship between TIPE2 and CD8, our preclinical data indicate that TIPE2 loss in MDSCs dictates the response to the combination therapy of the ferroptosis activator and immune therapy." (PMID 39851538, 2025). "TIPE2 upregulation in tumor cells can cause cell death and significantly reduce Ras-induced tumorigenesis in mouse models." (PMID 39851538, 2025). "More importantly, TIPE2-deficient MDSCs achieved the full anti-tumor therapeutic potential of IKE-induced ferroptosis therapy and a PD-L1 blockade." (PMID 39851538, 2025). "More importantly, TIPE2-deficient MDSCs achieve the full anti-tumor therapeutic potential of IKE-induced ferroptosis therapy and the PD-L1 blockade." (PMID 39851538, 2025). "As a conclusion, TIPE2-deficient MDSCs sensitized tumor to ferroptosis therapy by turning cold tumors into hot tumors." (PMID 39851538, 2025). "TIPE2 expression was negatively associated with tumor size, TNM stage and metastasis of lymph nodes." (PMID 33850476, 2021). "Univariate analysis suggested that tumor stage, tumor differentiation and TIPE2 levels were significantly associated with the OS of PDAC patients." (PMID 33850476, 2021). "In the present study, we reported that the downregulation of TIPE2 mRNA expression was significantly associated with venous invasion, primary tumor size and TNM stage." (PMID 31661000, 2019). "In HCC patients, TIPE2 mRNA was significantly associated with venous invasion, tumor size and tumor node metastasis stage." (PMID 31661000, 2019). "Further analysis revealed that TIPE2 expression decreased with tumor progression, and reduced TIPE2 expression was significantly associated with tumor size, capsule infiltration, peripheral infiltration and T stage." (PMID 30186591, 2018). "TIPE2 expression was negatively associated with tumor size and mitotic count, as well as the ratio of Ki-67 positive cells, which has been suggested as an alternative for mitosis counting." (PMID 30534358, 2018). "In the present study, we found that TIPE2 expression was significantly associated with tumor invasiveness." (PMID 30186591, 2018). "Further analysis of clinical characteristics revealed that TIPE2 was closely associated with tumor differentiation, stages and lymph node metastasis." (PMID 30157801, 2018). "Taken together, we propose that TIPE2 is centralized in a pathogenic network of infection, inflammation, DNA damage, and tumor formation." (PMID 27696294, 2016). "Clinical information from a cohort of 112 patients reveals that loss or reduced expression of TIPE2 in primary HCC tissues is significantly associated with tumor metastasis." (PMID 24274578, 2013). "Survival analyses demonstrated that TIPE2 expression was associated with overall survival and disease-free survival across multiple cancer types, exhibiting directionally heterogeneous effects depending on tumor context." (PMID 41993135, 2026). "In addition, tumor-derived ROS induce TIPE2 expression in MDSCs, but TIPE2-deficient MDSCs lowers ROS release, suggesting that TIPE2 can govern ROS production through a positive feedback loop in MDSCs." (PMID 39851538, 2025). "We observed that TIPE2 loss notably reduced the CD71 expression in IKE-treated tumor PMN-MDSCs compared to IKE-treated WT tumor PMN-MDSCs, but TIPE2 deficiency did not change the CD71 expression of IKE-treated tumor M-MDSCs compared to IKE-treated WT tumor M-MDSCs." (PMID 39851538, 2025). "Mice with systemic TIPE2 deficiency are resistant to tumor growth suggesting that TIPE2 may suppress anti-tumor immune responses." (PMID 36187930, 2022). "Taken together, these results indicated that TIPE2 may be an effective potential immunohistochemical marker for assessing the risk of tumor progression and predicting prognosis." (PMID 33850476, 2021). "Furthermore, the mutation of TIPE2 in sites which binds to Rac1, reversed this inhibitory effect on tumor cell invasiveness." (PMID 30186591, 2018).
tumor (continued). "By suppressing angiogenesis, the volume of tumors with high TIPE2 expression may be limited due to that enough nutrition was not available, which may account for the phenomenon that decreased TIPE2 expression was associated with larger primary tumor size." (PMID 27556698, 2016). "However, further analysis revealed that TIPE2 expression decreased with tumor progression and its reduced expression in tumor tissues was significantly associated with large primary tumor size and more lymph node metastasis." (PMID 27556698, 2016). "Since TNM stage III-IV means that tumor is accompanied with vascular invasion or distant metastasis, the data suggests that the loss or low expression of TIPE2 may be associated with metastasis of HCC." (PMID 24274578, 2013). "In murine tumor models, deletion of TIPE2 enhances the expression of anti-tumor mediators and diminishes the expression of pro-tumor mediators within myeloid-derived suppressor cells, thus hampering tumor growth." (PMID 41563279, 2026). "For example, TIPE2 suppresses tumor growth by directly binding to RAC1, whereas TIPE3 promotes pancreatic cancer progression in a RAC1-dependent manner." (PMID 40904408, 2025). "Among the choline-containing phospholipids, the content of either PC (18:0/20:4), PC (18:0/22:4), or PC (18:0/22:6) was also reduced in TIPE2−/− tumor MDSCs than in WT tumor MDSCs." (PMID 39851538, 2025). "On another hand, TIPE2 expression in MDSCs contributed to tumor immunosuppression, thus promoting tumor progression." (PMID 39851538, 2025). "Different from the oncogenic role of TIPE3, TIPE2 predominantly functions as a tumor suppressor in various types of cancers." (PMID 40904408, 2025). "Surprisingly, IKE-treated TIPE2−/− tumor MDSCs substantially increased the nitric oxide (NO) level compared to IKE-treated WT tumor MDSCs." (PMID 39851538, 2025). "Transferring Tipe2−/− NK cells into MC38 tumor‐bearing mice conferred superior tumor control over wild‐type NK cells, confirming the improved tumor control by Tipe2−/− NK cells." (PMID 36807566, 2023). "We divided the samples in each dataset into two groups according to TIPE2 expression and analyzed the tumor-infiltrating immune cells between patients with low and high TIPE2 expression." (PMID 36801818, 2023). "Then the RNA-seq-based transcriptome analysis was utilized to elucidate the detailed molecular mechanism by which TIPE2 exerts its anti-tumor effects in EOC." (PMID 36801818, 2023). "Correlation analysis between TIPE2 and related genes and markers of immune cells in Tumor Immune Estimation Resource (TIMER)." (PMID 36801818, 2023). "Since perforin‐dependent cytolytic activity represents the major antitumor effector function of NK cells, we first analyzed the correlation of Tipe2 (EGFP) versus perforin expression in tumor‐infiltrating NK cells in MC38 tumor‐bearing Tipe2 reporter mice." (PMID 36807566, 2023). "TIPE2 also elicits its anti-tumor activity by activating T and NK cells while inhibiting FoxP3+ Treg cells in the TME." (PMID 36801818, 2023). "During this process, TIPE2, a previously identified checkpoint molecule in NK cell maturation and tumor immunity, also represents a checkpoint regulating NK cell helper function in supporting the antitumor CD8+ T cell response." (PMID 36807566, 2023). "Overexpression of TIPE2 increased cell apoptosis and greatly reduced Ras-induced carcinogenesis, indicating its potential role as a neoplastic disease suppressor." (PMID 36801818, 2023). "We found that NK‐specific Tipe2 deletion alone displayed comparable or even slightly better tumor control over anti‐PD‐L1 immunotherapy in control mice." (PMID 36807566, 2023). "Of these genes, TNFAIP8, TIPE1, and TIPE3 are known to greatly influence tumor occurrence and development, while TIPE2 is mainly involved in innate immunity and acquired immunity." (PMID 36118167, 2022).
tumor (continued). "Lastly, intravenous injections of diverse tumor cell types in Ncr1iCrexTipe2flox mice show decreased tumor growth and higher numbers of NK cells suggesting that TIPE2 inhibits NK cell antitumor immunity." (PMID 36569860, 2022). "Ten high-power fields were randomly selected from each specimen to observe and record the percentage of immunoreactive cells of TIPE2 in tumor cells (grade 0–4) and the corresponding immunostaining intensity (grade 0–3)." (PMID 35388275, 2022). "BrdU labeling showed more positive cells (tumor cells) in AOM/DSS treated WT compared to matched Tipe2 KO mice, but markedly decreased in anti-CD25 injected mice." (PMID 34702807, 2021). "In the present study, we demonstrated for the first time that TIPE2 expression was upregulated in early tumor tissues but the levels of TIPE2 decreased in advanced stage PDAC tissues." (PMID 33850476, 2021). "TIPE2 can regulate tumorigenesis not only directly from the inside of tumor cells, but also indirectly via immune cells." (PMID 34249724, 2021). "As an important regulator of tumor microenvironment, TIPE2 was found to significantly inhibit oncogenic progression through activating T and NK cells, and inhibiting FoxP3+ Treg cells in tumor microenvironment." (PMID 34249724, 2021). "Collectively, these results showed that TIPE2 inhibited tumor cell proliferation and promoted apoptosis in PDAC cells." (PMID 33850476, 2021). "Consistent with the IHC results, TIPE2 was upregulated in tumor tissues and PBMCs compared to normal tissues in early stages of PDAC." (PMID 33850476, 2021). "In the present study, TIPE2 expression was higher in early tumor tissues than in adjacent normal tissues, but TIPE2 expression decreased in advanced stage PDAC tissues." (PMID 33850476, 2021). "Multivariate analysis confirmed that tumor stage, tumor differentiation and TIPE2 expression were independent prognostic factors for PDAC patients." (PMID 33850476, 2021). "We collected 74 cases of PDAC tumor tissues and corresponding 57 cases of adjacent normal tissues to clarify the expression of TIPE2." (PMID 33850476, 2021). "We found that the overexpression of Tipe2 in tumor cells markedly decreased the protein level of c-Myc, but increased the phosphorylation level of p-Smad3." (PMID 34702807, 2021). "Very interestingly, the tumor number from anti-CD25 treated Tipe2-/- mice was significantly lower compared with anti-CD25 treated Tipe2+/+ controls, especially tumors with size more than 2 mm." (PMID 34702807, 2021). "To explore the role of TIPE2 in pancreatic tumorigenesis in vivo, we established the subcutaneous xenograft tumor model using nude mice." (PMID 34249724, 2021). "Meanwhile, the role of TIPE2 in the anti-tumor effect of gracillin was elucidated via the use of siTIPE2 RNA." (PMID 34630074, 2021). "Overexpression of TIPE2 in tumor cells induced cell apoptosis and significantly inhibited Ras-induced tumorigenesis through binding to Ras-interacting domain of RGL and inhibiting the activation of Ral." (PMID 34249724, 2021). "Meanwhile, we demonstrated that TIPE2 expression is closely related to tumor proliferation and apoptosis." (PMID 33850476, 2021). "The expression of TIPE2 was closely related to tumor stage (P<0.001), lymph node metastasis (P<0.001) and tumor diameter (P=0.030)." (PMID 33850476, 2021). "In this manner, TIPE2 acts as an important regulator in tumor development and tumor microenvironment during oncogenic progression." (PMID 34249724, 2021). "IHC results showed that TIPE2 staining in early tumor tissues was significantly increased compared to that in adjacent normal tissues (P<0.001)." (PMID 33850476, 2021). "TIPE and TIPE3 had been confirmed to possess a carcinogenic effect in tumor development, while TIPE2 was proved to play opposite roles in cell death and tumorigenesis." (PMID 34188681, 2021). "Genetic deletion of TIPE2 or pharmacological inhibition of ROS markedly reduced tumor growth in mice." (PMID 32509781, 2020).
tumor (continued). "It was proven that TIPE2 knockdown promoted the growth of this tumor through angiogenesis modulation." (PMID 33276489, 2020). "In HCC patients, the expression of TIPE2 mRNA had a significant relationship with venous invasion, tumor size and tumor node metastasis (TNM) stage." (PMID 31661000, 2019). "Tumour necrosis factor‐α‐induced protein 8‐like 2 (TIPE2) is a tumour suppressor in many types of cancer." (PMID 30637920, 2019). "Lower TIPE2 mRNA expression tends to show a higher incidence of venous invasion or larger tumor size." (PMID 31661000, 2019). "In line with our findings, a study carried out by Li and their group showed TIPE2 to be upregulated in NSCLC tumor tissues when compared with adjacent normal tissues." (PMID 31817720, 2019). "TIPE2 mainly acts as a tumor suppressor by suppressing tumor proliferation, migration, invasion and angiogenesis in a variety of tumors." (PMID 30186591, 2018). "In the present study, we demonstrated that TIPE2 serves as an ideal immunohistochemical biomarker for the differentiation of tumor aggressiveness in PTC." (PMID 30186591, 2018). "Mechanically, TIPE2 suppressed tumor invasiveness by inhibiting Rac1, which subsequently decreased the expression of uPA and MMP9." (PMID 30186591, 2018). "All these results indicate that TIPE2 is a potential biomarker for predicting tumor aggressiveness and suppresses tumor invasiveness in a Rac1-dependent manner in PTC." (PMID 30186591, 2018). "It was found that TIPE2 expression was gradually decreased in accordance with GIST risk grades and negatively associated with tumor size, mitotic count and risk category." (PMID 30534358, 2018). "Here we demonstrated that TIPE2 suppressed tumor aggressiveness via inhibiting Rac1, which subsequently decreased the expression of uPA and MMP9 in PTC cells." (PMID 30186591, 2018). "Our present studies indicated that the expression of TIPE2 was significantly decreased in tumor tissues compared to distant mucosa tissues in human GC patients." (PMID 30157801, 2018). "Taken together, these data suggested that TIPE2 acts as a tumor suppressor by suppressing the viability, proliferation, migration and invasion of PTC cells." (PMID 30186591, 2018). "TIPE2 suppressed a number of malignant behaviors of tumor cells, such as viability, proliferation, migration and invasion." (PMID 30186591, 2018). "Results showed that TIPE2 staining was low in adjacent normal tissues, while strong TIPE2 expression was observed in tumor tissues." (PMID 30186591, 2018). "We measured TIPE2 expression in tumor samples from 46 human GC patients at mRNA level by Realtime PCR and in 68 pairs of GC tissues at protein level by immunohistochemistry." (PMID 30157801, 2018). "In contrast, the tumor growth and tumor volume derived from the Changliver-TIPE2 knockdown cells are much increased compared to the tumors of Changliver cells itself." (PMID 27696294, 2016). "The decreased TIPE2 expression in NSCLC is a promising biomarker for predicting tumor lymph node metastasis." (PMID 27556698, 2016). "The results of Huh7-TIPE2 and Changliver-TIPE2 knockdown xenografts in nude mice suggest that the tumor volume and growth speed of Huh7-TIPE2 overexpression cells are much reduced compared to Huh7 itself." (PMID 27696294, 2016). "Targeting Rac1 and subsequently inhibiting its activity make TIPE2 a potential therapeutic strategy to suppress the invasiveness of tumor cells." (PMID 27556698, 2016). "A recent study showed that expression of TIPE2 was reduced in peripheral blood mononuclear cells and tumor tissues from HBV-infected patients compared to healthy individuals." (PMID 27696294, 2016). "As the migration and invasion capacities of tumor cells are key steps during the process of tumor metastasis, we next assessed the effect of TIPE2 on migration and invasion in NSCLC cells." (PMID 27556698, 2016).
tumor (continued). "Taken together, we deduced that TIPE2 expression was up-regulated with the process of metaplasia and tumorigenesis, and with the development of tumor, the expression of TIPE2 decreased, accompanied with the enhanced malignant behaviors of tumor cells." (PMID 27556698, 2016). "The results showed that expression of TIPE2 is significantly reduced in tumor tissues compared to that in the paracarcinoma tissues from HCV-positive HCC patients." (PMID 27696294, 2016). "Recently, researches on TIPE2 and its related effects on tumor development have become a research focus." (PMID 27556698, 2016). "To examine the potential roles of TIPE2 in the inhibition of HCC tumor growth, we performed plate colony formation assay using Huh7-TIPE2 overexpression and Changliver-TIPE2 knockdown stable cell lines in vitro." (PMID 27696294, 2016). "From the curve of tumor growth, the tumor volume of TIPE2-expression groups were significantly decreased compare to the vector groups." (PMID 25946186, 2015). "The overall mean tumor size of TIPE2-expression groups was significantly smaller than that of the vector groups, which was consistent with the tumor weights." (PMID 25946186, 2015). "As shown in, in non-tumor lung tissues, TIPE2 strong staining was observed in lung epithelial alveolar cells and bronchial cells." (PMID 25946186, 2015). "Recently, our previous research has shown that TIPE2 expression is completely lost or significantly downregulated in human primary HCC but is high in all the paired adjacent non-tumor tissues." (PMID 24274578, 2013). "Consistent with this, silence of Rac1 expression by specific siRNA abolished the inhibition effect of TIPE2 on migration and invasion of tumor cells." (PMID 24274578, 2013). "The forced expression of TIPE2 in HCC-derived cell lines markedly inhibits tumor cell growth, migration and invasion in vitro and suppresses growth and metastasis of HCC in vivo." (PMID 24274578, 2013). "And after the tumor was transplanted into liver for 35 days, TIPE2 expression was still slightly detectable in some of tumor tissues." (PMID 24274578, 2013). "Our previous research has shown that TIPE2 is downregulated in human primary HCC compared with the paired adjacent non-tumor tissues." (PMID 24274578, 2013). "Collectively, human TIPE2 is an endogenous inhibitor of Rac1 by which it functions as a tumor suppressor to control cell proliferation, migration and invasion." (PMID 24274578, 2013). "In the present study, the TIPE2 mRNA expression of renal tumor tissues from RCC patients was analyzed prior to treatment with any anti-tumor drugs." (PMID 24137373, 2013). "The emphasis of our next study will be on investigating the potential effects of anti-tumor drugs and surgical intervention on TIPE2 expression, and assessing the stability of the TIPE2 expression profile over time in individual patients." (PMID 24137373, 2013). "To provide in vivo evidence that TIPE2 suppresses HCC tumor growth and metastasis, we established two xenograft tumor models in nude mice, subcutaneous xenograft tumor model and liver orthotopic transplanted tumor model using HCCLM3 cells." (PMID 24274578, 2013). "In present research, after last TIPE2 plasmid injection, high level of TIPE2 expression was detected in subcutaneous tumor." (PMID 24274578, 2013). "Importantly, IKE-treated TIPE2−/− tumor MDSCs pretreated with L-NAC further reduced their ability to block T cell proliferation, compared with those from IKE-treated WT controls." (PMID 39851538, 2025). "Furthermore, treatment with the ROS inhibitor N-acetyl cysteine (L-NAC) led to a more significant reduction in CD71 expression in IKE-treated TIPE2−/− tumor MDSCs compared to IKE-treated WT tumor MDSCs." (PMID 39851538, 2025).